FNDC7 (fibronectin type III domain containing 7)
Synonyms: FLJ35838
Tractability: Antibody: UniProt places it where antibodies can reach, with high confidence; UniProt predicts a signal peptide or a membrane-spanning region; its Gene Ontology location is reachable by antibodies, with medium confidence.
Gene: Protein-coding gene on chromosome 1 (108,712,907 to 108,746,052, forward strand). Ensembl gene ENSG00000143107.
Subcellular location: Secreted
Subcellular location (Human Protein Atlas): Actin filaments; Nucleoplasm; Predicted to be secreted
Gene Ontology:
Cellular component: non-collagenous component of interstitial matrix; extracellular region
Genetic constraint (gnomAD): Loss-of-function variants: 57 observed, 70.04 expected, observed/expected ratio (o/e) 0.81, 90% interval 0.66 to 1.01. The upper end of that interval is the gene's LOEUF score, 1.01, which puts it in group 4 of 6, group 1 being the genes least tolerant of losing a copy. Missense variants: 757 observed, 870.58 expected, observed/expected ratio (o/e) 0.87, 90% interval 0.82 to 0.92. Synonymous variants: 285 observed, 322.36 expected, observed/expected ratio (o/e) 0.88, 90% interval 0.8 to 0.98.
Homologues: Orthologues: chimpanzee FNDC7 (98% identical), macaque FNDC7 (96% identical), dog FNDC7 (89% identical), pig FNDC7 (89% identical), rabbit FNDC7 (88% identical), guinea pig FNDC7 (86% identical), mouse Fndc7 (86% identical), rat Fndc7 (86% identical), tropical clawed frog fndc7 (55% identical), zebrafish fndc7a (41% identical). Paralogues in human: FN1 (15% identical), TNR (14% identical), TNN (13% identical), TNC (13% identical), TNXB (12% identical), ANGPTL2 (11% identical), ANGPT1 (11% identical), ANGPT2 (11% identical), ANGPTL1 (10% identical), ANGPTL6 (10% identical), ANGPT4 (10% identical), ANGPTL3 (10% identical), and 13 more.
Diseases named in the same sentence as FNDC7 in open-access papers:
FNDC7 is named in the same sentence as 10 diseases in open-access papers, as found by Europe PMC text mining. Sharing a sentence is not in itself a finding about the gene and the disease. The quoted sentences say what the papers report.
liver cancer (1 paper, 2022). An epithelial or non-epithelial malignant neoplasm that arises from the liver. "With respect to liver cancer, high expression of FNDC1, FNDC3A, FNDC5, and FNDC7 was correlated with better prognosis, but increased expression of FNDC6 and FNDC8 was correlated with poor OS and PFS, respectively." (PMID 36626432, 2022).
lung adenocarcinoma (1 paper, 2022). A carcinoma that arises from the lung and is characterized by the presence of malignant glandular epithelial cells. "However, in lung adenocarcinoma, all members of the FNDC family, except FNDC7 and FNDC8, are interrelated to RFS/OS and FP." (PMID 36626432, 2022). "Furthermore, the whole FNDC family, except for FNDC7 and FNDC8, was found to have substantial predictive effects in lung adenocarcinoma, but not in squamous cell lung cancer." (PMID 36626432, 2022).
cancer (1 paper, 2022). A tumor composed of atypical neoplastic, often pleomorphic cells that invade other tissues. "Oncomine revealed that the mRNA expression levels of FNDC1, FNDC3A, and FNDC3B were higher in most malignancies than in normal tissues, but the mRNA expression levels of FNDC4, FNDC5, FNDC7, and FNDC8 were downregulated in most cancers when compared with normal tissues." (PMID 36626432, 2022).
FNDC7 also shares sentences with these, for which no sentence is quoted: lung carcinoma (1 paper); mental disorder (1); nervous system diseases (1); ovarian carcinoma (1); ovarian serous cystadenocarcinoma (1); squamous cell lung carcinoma (1); tumor (1).